RPL10P3 (ribosomal protein L10 pseudogene 3)
Synonyms: bA567J2.2
Gene: Processed pseudogene on chromosome 9 (117,180,628 to 117,181,095, reverse strand). Ensembl gene ENSG00000230734.
Diseases named in the same sentence as RPL10P3 in open-access papers:
RPL10P3 is named in the same sentence as 1 disease in open-access papers, as found by Europe PMC text mining. Sharing a sentence is not in itself a finding about the gene and the disease.
RPL10P3 shares sentences with these, for which no sentence is quoted: Sepsis (1 paper).